SOD2 (superoxide dismutase 2)
Diseases named in the same sentence as SOD2 in open-access papers (continued):
Sharing a sentence is not in itself a finding about the gene and the disease.
pancreatic cancer (continued). "Furthermore, we demonstrate that sensitivity of pancreatic carcinoma cell lines to 2-methoxyestradiol correlates with SOD2 expression and SOD2 modulation can alter the sensitivity of these cells." (PMID 17895890, 2007). "While lowered SOD2 expression in itself might present treatment options for pancreatic carcinoma, the furthered understanding of the consequences of altered SOD2 expression illuminates other mechanisms that could be involved in the pathology of pancreatic cancer, suggesting further treatments." (PMID 17895890, 2007). "Real-time PCR was utilized to examine changes in the mRNA expression of antioxidant enzymes, specifically SOD2 and GPx, in MIA-PACA2 pancreatic cancer cells following treatment with varying concentrations of Mito-FF." (PMID 39859498, 2025). "We established and validated a prognostic model for pancreatic cancer with 7 signatures, including ADH1C, APOE, RAP1GAP, NPC1L1, P4HB, SOD2, and TNFSF10." (PMID 38685045, 2024). "In particular, aggressive pancreatic cancer cell lines such as HPAC, AsPC-1, Capan-1, and PANC-1 displayed the highest levels of SOD2." (PMID 37891871, 2023). "The Annexin-V-FITC and PI-PE apoptosis detection kit was used to analyze the regulation of apoptosis in SOD2-silenced and SOD2-overexpressed HPAC pancreatic cancer cells." (PMID 37891871, 2023). "We also found that NB decreases SOD2 expression and negatively impacts the PI3K/Akt/mTOR pathway, leading to the inhibition of growth in pancreatic cancer cells." (PMID 37891871, 2023). "Further, KLF11 suppressed expression of the ROS scavenger genes superoxide dismutase 2 (SOD2) and catalase 1 in pancreatic cancers." (PMID 35406507, 2022). "SOD2 expression is higher than SOD1, SOD3, and CAT in pancreatic cancers." (PMID 37891871, 2023). "In conclusion, our data delineate a potential anticancer mechanism of action of NB, which is NB induces ROS generation mainly through the inhibition of SOD2, which inhibits proliferation via PI3K/Akt signaling pathway and metastasis while increasing apoptosis in pancreatic cancer cells." (PMID 37891871, 2023). "Moreover, we detected AgNP-induced disturbance of antioxidant system (SOD1, SOD2, GPX-4, CAT, and SOD3) in pancreatic cancer cells." (PMID 30186549, 2018). "Several reports have demonstrated decreased expression of SOD2 in pancreatic carcinoma without determining the underlying cause." (PMID 17895890, 2007). "The mechanism of decreased SOD2 expression in pancreatic carcinoma has not been previously determined." (PMID 17895890, 2007). "The invasion of pancreatic cancer cells resulting from the activation of the H2O2/MAPK axis under high glucose conditions is effectively inhibited by PD 98059 (ERK inhibitor), SB 203580 (p38 MAPK inhibitor), polyethylene glycol-conjugated catalase (PEG-CAT), or the siRNA specific to SOD2." (PMID 26439801, 2015).
endothelial dysfunction (41 papers, 2009 to 2025). In vascular diseases, endothelial dysfunction is a systemic pathological state of the endothelium (the inner lining of blood vessels) and can be broadly defined as an imbalance between vasodilating and vasoconstricting substances produced by (or acting on) the endothelium. "SIRT3 deficiency and redox inactivation of SIRT3 result in SOD2 inactivation and contribute to the pathogenesis of endothelial dysfunction and hypertension." (PMID 32015327, 2020). "Also, Sirt-3 deficient mice on a high-cholesterol diet developed endothelial dysfunction that was dependent on low superoxide dismutase 2 activity (SOD2) and high ROS generation." (PMID 33499277, 2021). "The physiological importance of SOD2 is high-lighted by the finding that in contrast to other SOD isoforms, the deficiency of SOD2 causes early neonatal death in gene knockout mice and endothelial dysfunction in carotid artery of proatherogenic apolipoprotein E (ApoE)-deficient mice." (PMID 23442817, 2013). "The proposed mechanism states that SIRT3 deacetylates and activates SOD2, which protects against endothelial dysfunction and HT." (PMID 34829803, 2021). "In our study, ALA supplementation rescued SIRT3 reduction and SOD2 hyperacetylation, improved endothelial dysfunction and reduced blood pressure elevation in hypertensive animals." (PMID 32015327, 2020). "White blood cells from mice with heterozygous mitochondrial superoxide dismutase (MnSOD or SOD2) deficiency showed higher NOX-2 activity and endothelial dysfunction, all of which were further aggravated upon challenges with AT-II." (PMID 31341533, 2019). "The present studies, therefore, strongly suggests that IL-6 is an important contributor of T2D-mediated endothelial dysfunction, especially through elevated O2- production and attenuated SOD2 protein expression." (PMID 29095915, 2017). "In addition, our previous investigations demonstrated that superoxide dismutase 2 (SOD2) as a down-stream target of SIRT3 participated in the protective effect of endothelial dysfunction in diabetic mice by DHY." (PMID 36671063, 2023). "In addition, cigarette smoke, a validated risk factor for CVD, decreases endothelial SIRT3 levels and leads to SOD2 hyperacetylation and endothelial dysfunction." (PMID 34829803, 2021). "SOD2 is also shown to protect against endothelial dysfunction in carotid artery of ApoE−/− mice." (PMID 23442817, 2013). "However, it is noteworthy that during the course of sepsis, neutrophils can also mitigate oxidative stress and endothelial dysfunction by releasing extracellular vesicles carrying superoxide dismutase 2 (SOD2), thus alleviating symptoms of disseminated intravascular coagulation (DIC)." (PMID 40476000, 2025). "Not surprisingly, many of the most upregulated genes are well-known markers of endothelial dysfunction (e.g., SELE, ICAM1, SOD2, IL8, IL1B)." (PMID 31287004, 2019). "It was demonstrated that the genes associated with TNF-α signaling (TRAF1, TNFAIP2, and NFKBIZ) and oxidative stress regulation (SOD2) were significantly upregulated, suggesting that NS1 activates pathways critical for endothelial dysfunction and vascular inflammation." (PMID 40508120, 2025). "Furthermore, it is known that miR-21 represses RhoB expression in endothelial cells, leading to angiogenesis inhibition, and regulates superoxide dismutase 2 (SOD2), as well as Sprouty 2, resulting in NO (nitric oxide) reduction and endothelial dysfunction." (PMID 38921830, 2024).
Sepsis (39 papers, 2007 to 2026). Sepsis is defined as life-threatening organ dysfunction caused by a dysregulated host response to infection. "Some findings are consistent with our study, for instance, IL17A, IL1B, MBL, NOD2, PPARG and SOD2 genes were associated with sepsis." (PMID 40168842, 2025). "Then we provide evidence for mitochondrial abnormalities as major causes of post-sepsis muscular dysfunction by utilizing a transgenic strain of mice overexpressing the mitochondria-localizing antioxidant enzyme manganese superoxide dismutase (MnSOD or SOD2)." (PMID 39563237, 2024). "In a mouse model of sepsis, circulating neutrophils secrete mitochondria-containing EVs highly enriched with SOD2." (PMID 41462703, 2025). "Next, we employed heterozygous Sod2 gene knock out mice (Sod2+/−) to directly assess the role of Sod2 in sepsis." (PMID 35933512, 2022). "Here the authors show neutrophils can prevent lethal coagulopathy via the production of extracellular vesicles that carry superoxide dismutase 2 in a murine model of lipopolysaccharide induced sepsis." (PMID 35933512, 2022). "Fourth, we believe the mechanism of melatonin-mediated SIRT3 activation in ameliorating sepsis is not limited to SOD2 deacetylation and warrants comprehensive investigation in the future." (PMID 33790896, 2021). "At enrollment, sepsis was associated with significant increases in the expression of mRNAs related to redox metabolism (myeloperoxidase, 64-fold; PRDX3, 2.6-fold; SOD2, 2.2-fold) and redox-responsive genes (FOXM1, 21-fold; SELS, 16-fold; GLRX2, 3.4-fold)." (PMID 29540208, 2018). "Our previous study found that SIRT1 activity and protein expression were greatly reduced following sepsis, accompanied by hyperacetylated manganese superoxide dismutase (SOD2)." (PMID 30533222, 2018). "We observed reduced SIRT1/3 activity, elevated acetylated SOD2 (ac-SOD2) levels and oxidative stress, and damaged mitochondria in RTECs following sepsis." (PMID 28003866, 2016). "Lung levels of SOD1 decreased 3 and 12 h after sepsis, but SOD2 and SOD3 increased, as well as SOD activity." (PMID 26266917, 2014). "Regarding oxidative stress, despite a 2-fold (p = 0.0016) increase in the 3-nitrotyrosine in Sepsis compared with Sham mice, the mRNA levels encoding the antioxidant enzymes Sod1, Sod2, and Cat were not different." (PMID 41315622, 2025). "It was noted that several genes with DRE were previously reported or implicated to play a role in sepsis or SAE, such as superoxide dismutase 2 (SOD2), Miat, peptidylarginine deiminase 2 (Padi2), Shank1, transcription factor 4 (Tcf4) and kinesin family member 3 (Kif3c)." (PMID 39135964, 2024). "The findings reveal that melatonin leverages a SIRT3-dependent pathway to enact deacetylation of SOD2, thereby safeguarding mitochondrial quality control in pulmonary epithelial cells, ultimately mitigating the sepsis-induced damages, inflammation, oxidative stress, and cell apoptosis." (PMID 38690282, 2024). "Consequently, Nrf2-induced antioxidant enzymes were dysregulated in the cortex as depicted by the decreased HO-1 and SOD-2 mRNA levels in the sepsis survivor mice." (PMID 37175808, 2023). "In addition to desposing damaged mitochondria through migrasomes, neutrophils also transport superoxide dismutase 2 (Sod2) through migrasomes to mediate antithrombosis, maintain endothelial homeostasis, and protect the host against sepsis." (PMID 37158915, 2023). "To evaluate more definitively whether Sod2 was necessary to mediate circulating neutrophils’ protective function in sepsis, we transferred neutrophils from LPS-challenged Sod2+/− mice or wild-type littermates into recipient mice followed by lethal LPS." (PMID 35933512, 2022). "Although Sod2+/− mice mounted a grossly normal response to LPS challenge, they succumbed sooner to LPS sepsis than their wild-type littermates, suggesting Sod2 was an essential effector maintaining homeostasis in LPS sepsis." (PMID 35933512, 2022).
Sepsis (continued). "SOD2 (mitochondrial superoxide dismutase; 12.5 and 5-fold increase at 2 and 24 hrs, respectively) plays a key role in free radical detoxification by destroying toxic free radicals produced within cells during sepsis." (PMID 17324256, 2007). "From these proteins, TNFα, IL-1α, Lck, NOS2, SOD2 and CD36 were selected for validation by Western blot on murine bone marrow-derived macrophages due to their relevant roles in the NF-κB, iNOS, oxidative stress, and phagosome signaling pathways, which are closely associated with sepsis pathogenesis." (PMID 40725160, 2025). "Also, the identified hub-gene signatures (e.g., NOS2, VEGFa, AKT, HO-1, SOD2) are useful for a deeper understanding of key signaling pathways-connection in sepsis development and may be helpful for early prediction of sepsis progression." (PMID 37407986, 2023). "Various mRNAs related to oxidative stress (myeloperoxidase, forkhead box protein M1, selenoprotein S, glutaredoxin 2, peroxiredoxin 3, superoxide dismutase 2 (SOD2)) were increased in EVs already at the day of diagnosis, indicating that EVs may contribute to an antioxidative host response in sepsis." (PMID 33336297, 2020). "Taken together, Sod2 is upregulated by circulating neutrophils upon LPS challenge, and it is a necessary effector molecule for neutrophils to restrain DIC in sepsis." (PMID 35933512, 2022). "Results showed that TNF, HSPA1A, HSPA1B, TREM1, SOD2 and MIF genes related to sepsis correspond to m6A-cis-eQTLs." (PMID 32174955, 2020). "Resveratrol, a known SIRT1 activator, effectively restore the activity of SIRT1/3 in sepsis rats with AKI, reduce the acetylation levels of recombinant superoxide dismutase 2 (SOD2), improve oxidative stress and mitochondrial function in renal tubular epithelial cells, and extend survival time." (PMID 40989844, 2025). "SOD2 and SOD3 increased after sepsis induction, but this was insufficient to protect the lung." (PMID 26266917, 2014). "There was no consistent pattern of gene expression; while sod1 and sod2 gene expressions increased 12 h after sepsis, sod3 gene expression decreased at this time point." (PMID 26266917, 2014). "Furthermore, an increase in the immunocontent of SOD2 was observed at all times, and there was an increase in the immunocontent of SOD3 at 6 and 12 h after sepsis induction." (PMID 26266917, 2014). "Here, in a CLP model, we demonstrated that during sepsis development, the levels of SOD2 and SOD3 increased in the lung, but these did not prevent nitrosative damage and inflammation." (PMID 26266917, 2014). "Sepsis induction reduced NF-κB and SOD2 protein expression but increased their acetylation, and this was accompanied by an increase in proinflammatory cytokines (TNF-α/IL-6/IL-10) and oxidative stress (indicated by reduced SOD2 activity, GSH content, GSH/GSSG ratio, and CAT activity)." (PMID 33790896, 2021). "Therefore, SOD2 plays a crucial protective role against oxidative damage; however, alteration in the SOD:CAT ratio, for example, an overexpression of SOD2, could lead to an increase in the levels of oxidative stress and morbidity in sepsis." (PMID 40725160, 2025). "Although augmentation of mitochondrial-oriented free radical scavengers such as MCAT and SOD-2 have shown promising results in animal models of ischemic cardiomyopathy as well as hypertensive heart failure, they have not been adequately explored in the context of sepsis." (PMID 28405943, 2017).
heart failure (38 papers, 2011 to 2025). Inability of the heart to pump blood at an adequate rate to meet tissue metabolic requirements. "Given the that SOD2 activity has been implicated in hypertrophy and heart failure progression, it will be important to see whether the extent of acetylation at these sites plays a role." (PMID 23844019, 2013). "The SIRT3 activator Honokiol improved exercise capacity in a myocardial infarction model mice with heart failure by improving mitochondrial function in their skeletal muscle through the reduction of SOD2 acetylation." (PMID 40511632, 2025). "The results showed that the expression levels of HIF-1α, IL10, PAD4, ACTG1, SOD2, and GAPDH were higher in heart failure patients with Qi deficiency and blood stasis syndrome compared to the HP group." (PMID 40671145, 2025). "Cardiomyocyte-specific SOD2 knockout in mice results in early-onset dilated cardiomyopathy and death by four months due to heart failure." (PMID 40722952, 2025). "Studies in mice have shown that the knockout of SOD2 causes the onset of DCM and subsequent death due to heart failure." (PMID 37373547, 2023). "In DOX-induced heart failure mice, SOD2, GPx-1, FOX3a, and SIRT3 expression are decreased, apoptotic cells and cleaved-caspase-3 expression are increased, as well as inflammatory cytokines such as IL-1β, IL-6, and TNF-α are increased." (PMID 34513812, 2021). "Our selected candidates included many therapeutic targets for heart failure including Atp2a2, Bcl2, Sod2 and Sirt323,24,28,41." (PMID 31705051, 2019). "A recent study has shown that patients with SOD2 defective may experience harmful increases in ROS in the neonatal heart, leading to the rapid development of heart failure and death." (PMID 37373547, 2023). "Therefore, GSH, Nrf2, SOD2, and CytC are related to the occurrence of heart failure during oxidative stress." (PMID 33362553, 2020). "Oxidative stress factors, such as Sod2, GPX1, etc., can efficiently suppress apoptosis of the myocardial cells and prevent the LPS-induced cardiac insufficiency and death." (PMID 30413180, 2018). "Similarly, in mouse hearts, SIRT4 inhibits SIRT3-mediated SOD2 activation potentially by competitively interacting with Mn-SOD for binding to SIRT3, leading to higher ROS levels and heart failure." (PMID 40799515, 2025).